VHL (von Hippel-Lindau tumor suppressor)
Diseases named in the same sentence as VHL in open-access papers (continued):
Sharing a sentence is not in itself a finding about the gene and the disease.
tumor (continued). "Data from both cells lines and tumour xenograft models extends this observation demonstrating conclusively that accumulation of proline-hydroxylated HIF-1α occurs in tumours and cell lines that express wild-type VHL." (PMID 24563687, 2014). "These genes include tumor suppressors or candidates (VHL, CTDSPL, LRRC3B, ALDH1L1, and EPHB1) and genes that were not previously considered as cancer-associated (e.g., LRRN1, GORASP1, FGD5, and PLCL2)." (PMID 24977159, 2014). "In this paper, Migdalska-Sek at al. assessed and compared the methylation level of 8 tumor suppressor genes, ARHI, CDH1, KCNQ1, MEST, p16INK4A, RASSF1A, SLC5A8 and VHL in PTC tumor tissues and matched adjacent noncancerous thyroid tissues." (PMID 25490036, 2014). "Interestingly, FLCN, similarly to VHL, is necessary for the activity of LC3C-mediated autophagic program that we have previously characterized as contributing to the tumor suppressing activity of VHL." (PMID 23922894, 2013). "To distinguish these tumors by the DNA methylation pattern more simply, we further selected four genes characteristically methylated among different tumor groups: ADRA1D, MGMT, VHL, and THBS1, and performed cluster analysis using the methylation average of 4 genes." (PMID 23638012, 2013). "The observed effects of FLCN knockdown on tumor growth are consistent with the negative effect of FLCN overexpression on the formation of tumors by 786-O VHL(−) cells, as observed by others." (PMID 23922894, 2013). "In nude mouse xenograft assays, both the pVHL30 (wildtype) and pVHL18 proteins function as tumour suppressors when introduced into clear-cell RCC cell lines lacking functioning VHL genes." (PMID 24062953, 2013). "The intensity of Aurora-A staining was correlated with the tumour grade (grade 4 vs. grade 2: p=0.0185), but not with the VHL status (p=0.0613), differently from what observed for the transcript level." (PMID 23785518, 2013). "FLCN contributes to VHL-induced tumor suppression by a mechanism that does not appear to involve activation of the mTOR pathway." (PMID 23922894, 2013). "Expression of GNE in UMRC2−/+VHL cells validated the changes found using the microarray, with reduced expression of GNE being seen in VHL transfectants and GNE levels were also upregulated in a significant proportion of tumours compared to normal renal tissue." (PMID 23970118, 2013). "Previous work showed methylation of the VHL promoter in the tumour with c.340G>C but not in the other three tumours." (PMID 22825683, 2012). "Similarly another study showed that HIF was the principal mediator of hypoxia-inducible gene deregulation in the VHL-/- renal cells and attenuation of HIF was sufficient to suppress the tumor forming capacity of these cells in nude mice." (PMID 22325146, 2012). "Unlike in the cell model, in human tumor tissue no change in expression of the mainly cytosolic SOD1 (P00441) was observed when comparing VHL- and SDHB-derived PHEOs/PGLs." (PMID 22859959, 2012). "In ccRCC deactivation of Von-Hippel-Lindau (VHL) gene contributes to the constitutive expression of hypoxia inducible factors 1 and 2 alpha (HIF-α), transcriptional regulators of several genes involved in tumor angiogenesis, glycolysis and drug resistance." (PMID 22804960, 2012). "An oxygen- and VHL/PHD-independent ubiquitination and proteasomal degradation of HIF-1α was observed after incubation of tumor cells with geldanamycin and the small molecule inhibitor NVP-AUY922 has been shown to reduce HIF-1α levels in human tumor xenografts." (PMID 22347438, 2012). "The discovery of VHL tumor-suppressor gene inactivation and consequent hypoxia-induced factor (HIF) activation of genes and downstream pathways important to tumor progression, have provided the impetus for development of new agents that target angiogenesis and proliferation pathways." (PMID 21834980, 2011).
tumor (continued). "Although it is likely that other actions of VHL contribute to its tumour suppressor action in the kidney, activation of HIF (and more specifically HIF-2α) has been shown to be necessary and sufficient for growth of VHL defective CCRCC cells in xenograft assays." (PMID 21386837, 2011). "There is specific evidence of PI3K pathway activation in RCC; it is constitutively activated in RCC cells regardless of VHL status, and activation is tumor specific." (PMID 21834980, 2011). "Therefore, these agents hold promise in tumor environments where VHL function is compromised, as in CCRCC or tumor hypoxia." (PMID 22172030, 2011). "This study demonstrated that the PI3K-Akt signaling pathway is constitutively activated in RCC cells, regardless of VHL status, and that activation of this pathway is tumor specific relative to corresponding normal renal tissue." (PMID 21834980, 2011). "Although much has been learnt about VHL in recent years, its tumour suppressor function is still not fully understood." (PMID 21791076, 2011). "This raises the interesting possibility that in cells that lack VHL and express HIF-1α, FIH-1 may favour tumour growth by decreasing the anti-proliferative consequences of HIF-1α activation and shifting the balance of HIF activation towards HIF-2α." (PMID 21386837, 2011). "Correspondingly, separate studies indicate that HIF-2α, but not HIF-1α, contributes to the growth of VHL null tumor xenografts." (PMID 21695080, 2011). "Moreover, we show that u-PAR, VEGFC, and HIF1α, among other targets, are being downregulated, and the tumour-suppressor genes FHIT, RASSF1, and VHL are upregulated upon Enz treatment." (PMID 20736951, 2010). "As the VHL gene is located on 3p25-26, this indicates that deregulation of VHL pathway is involved for ccRCC development only, but not for the other tumor subtypes." (PMID 20671976, 2010). "The promoter of von Hippel-Lindau (VHL) tumor suppressor gene is hypermethylated and its absence leads to a failure in degradation of hypoxia inducible factor (HIF)-1 whose accumulation favors tumor angiogenesis." (PMID 21108789, 2010). "Moreover, remarkably, it significantly upregulates the tumour-suppressor genes (FHIT, RASSF1, and VHL) that are known to be downregulated in NSCLC." (PMID 20736951, 2010). "It has been demonstrated that PAI-1 mRNA and protein levels were dramatically increased in RCC cells expressing mutant or lacking von Hippel-Lindau (VHL) tumour-suppressor genes compared with cells expressing wild type VHL." (PMID 21129210, 2010). "This may define a critical role for HIF-2α in the biology of VHL -/- CCRCC enabling greater growth; this demonstrates that in certain contexts HIF-1α can act as a tumor suppressor." (PMID 20652061, 2010). "The pseudohypoxic VHL-defective CCRCC cells show a bias toward HIF-2α, and overproduction of HIF2α (but not HIF1α), has been found to be sufficient to override the tumor suppressor function of VHL in xenograft studies." (PMID 20652061, 2010). "Unexpectedly, mean VEGF tumour expression and mean VEGF plasma levels were significantly increased in tumours with no VHL alteration as compared with tumours harbouring at least one VHL alteration." (PMID 19755989, 2009). "In a recent study we have demonstrated that the absence of VHL mutation, associated with low Carbonic Anhydrase IX (CAIX) tumour expression, was associated to a particular aggressive CCRCC phenotype." (PMID 19755989, 2009). "The importance of tumour angiogenesis in CCRCC development and spreading has been recently strongly validated by the proven efficacy of antiangiogenic drugs that target mainly the VHL/VEGF pathway." (PMID 19755989, 2009). "Although some studies have shown a positive relationship between genetic and epigenetic VHL gene alterations and VEGF tumour overexpression, literature results are conflicting especially regarding the association between VHL mutation, usual prognostic parameters and survival." (PMID 19755989, 2009).
tumor (continued). "At least two alterations of the VHL gene, potentially leading to biallelic alteration, were found in 68 tumours (66.7%), whereas no or a single alteration of the VHL gene was found in 34 patients (33.3%)." (PMID 19755989, 2009). "Conversely, unexpected low VEGF levels were found in tumours with VHL alterations, indicating that VHL alteration does not necessarily trigger tumour progression." (PMID 19755989, 2009). "Using immunohistochemistry, we confirmed our recently described observation that SDHB protein expression was completely lost in tumor cells of SDH-related patients and noticeably reduced in VHL-tumors, while it was still present in vascular endothelial and smooth muscle cells." (PMID 19763184, 2009). "Therefore, there was a rationale for analysing in a cohort of sporadic CCRCC the relationship between VHL alterations and VEGF plasma and tumour expression." (PMID 19755989, 2009). "These germline mutations are not solely found in classical families, but are also found in patients with a typical VHL tumour, lacking a positive family history." (PMID 17922902, 2007). "The quality of the DNA extracted from fixed tumours did not allow us to analyze the methylation status of the VHL promoter." (PMID 17997830, 2007). "In VHL-defective renal carcinoma cells (RCC), inactivation of HIF-α proteolysis upregulates both HIF-1α and HIF-2α with global induction of HIF target gene expression, stimulating investigations of the role of the HIF pathway in tumour development." (PMID 17387348, 2007). "We applied two-dimensional hierarchical clustering to examine the relationship between the loci and the tumor and non-tumor lung samples (VHL was omitted because it showed no DNA methylation in any samples)." (PMID 17967182, 2007). "We determined that the lack of VHL tumor suppressor activity stabilized HIF-2α protein and increased MT1-MMP expression through direct transcriptional transactivation by HIF-2α." (PMID 17140440, 2006). "Furthermore, HIF-1α can trigger the synthesis of lincRNA-p21, which stabilizes the protein level of HIF-1α and increases the glycolytic metabolic activity of tumor cells by preventing the ubiquitination and destruction of HIF-1α by interfering with the interaction between VHL and HIF-1α." (PMID 41614928, 2026). "In these patients, the negative family history of VHL diagnosis suggests that the component tumor may be sporadic or constitutional with low penetrance." (PMID 40647474, 2025). "A subset of patients in Cohort 2 did not undergo constitutional cancer testing, and it is not clear whether the VHL alterations detected through tumor profiling—most of which were deletions—were truly somatic." (PMID 40647474, 2025). "HIF1A had a tendency to be downregulated in tumor tissue independent of VHL alteration." (PMID 40332447, 2025). "However, according to proteinatlas.org, VHL expression is ubiquitous in major organs, which does not explain the tumor-selective RIPK1 degradation induced by LD4172." (PMID 39681571, 2024). "This suggests that the VHL prediction model may not have effectively learned to fully focus on the tumor tissue or that it discovered pathological features outside the tumor region that are relevant to the prediction." (PMID 39166457, 2024). "The presence of bilateral tumours in patients with VHL is not an unexpected finding." (PMID 39673085, 2024). "However, further analysis shows that the differentially expressed genes in the tumor component mainly involve immune functions, suggesting that these genes are lost in VHL mutant cultures due to the lack of immune cells." (PMID 39600908, 2024). "However, due to the tumour suppressor role of VHL, the PROTAC-mediated degradation of VHL may promote tumorigenesis, necessitating further mechanistic research by the homo-VHL PROTAC probes to understand the cellular action." (PMID 37667522, 2023). "Specifically, the inactivation of VHL renders VHL− tumor cells highly motile but non-proliferative." (PMID 37069149, 2023).
tumor (continued). "Indeed, ccRCC is a highly angiogenic malignancy due to the fact that the tumor cells overproduce hypoxia inducible VEGFA mRNAs in the absence of VHL, irrespective of oxygen availability." (PMID 36831657, 2023). "Whereas germline VHL mutations commonly predispose individuals to the development of multiple tumours, homozygous carriers of germline VHLR200W mutations show total absence of tumour development despite increased HIFα signalling." (PMID 35760869, 2022). "In ccRCC, the inactivation of VHL leads to the protein accumulation of HIF-1a and HIF-2a, which translocate to the nucleus and regulate a variety of gene expression programs at the transcriptional level to promote tumor growth, tumor metastasis, and neo-angiogenesis." (PMID 36611966, 2022). "Bi-allelic inactivation of the VHL gene leads to constitutive activation of the hypoxia-inducible factors (HIF-1 and HIF-2), promoting neovascularization through downstream targets such as vascular endothelial growth factor (VEGF), which is strongly expressed in the tumor cells of ELSTs." (PMID 35546652, 2022). "However, its molecular tumorigenesis mechanisms were not described until the 1990s and beyond when the VHL gene, a tumor suppressor gene, was localized to chromosome 3 (3p25-3p26)." (PMID 36421797, 2022). "Several well-described pro-tumor properties of CAFs are mediated through hypoxia-inducible-factor-1 (HIF1), a pathway that drives oncogenesis in kidney cancer and is upregulated in the majority of ccRCC tumors via alteration of the von-Hippel Lindau (VHL) gene." (PMID 34359645, 2021). "Therefore, if SDH genetic testing of an SDHB-immunonegative tumor does not show a mutation, SDHC promoter methylation, VHL, and/orNF1 molecular testing is recommendable." (PMID 34181326, 2021). "As 3D-conformation has been shown to influence gene expression and regulation in tumor cells, investigating MYC, HIF1A, VHL and PHD gene expression and relevant miRNAs levels could provide insights into the significance of HIF1-α levels in SK-LMS-1 jumbo spheroids." (PMID 34439199, 2021). "Molecular alterations in RCC tumors have been extensively studied in the last decade, especially in ccRCC but neither identified mutations (e.g.,: VHL, BAP1, PBRM1, SETD2, KDM5C, MTOR) nor transcriptome-based ccRCC tumor sub-classification have straightforward clinical relevance." (PMID 33535553, 2021). "Although the role of the VHL/HIF pathway is well described in RCC tumor initiation, inactivation of VHL alone may not be sufficient to drive ccRCC tumorigenesis." (PMID 34609963, 2021). "In PC, miR-21 contributes to tumor growth, invasion, and chemoresistance by positively regulating the expression of invasion-related genes including MMP-2/9 and vascular endothelial growth factor (VEGF), and negatively regulating the expression of the tumor-suppressor gene, VHL." (PMID 34066762, 2021). "The wild type status of the remaining tumor does not exclude a large deletion of the chromosome 3p locus, encompassing VHL, and could not be detected by sequencing." (PMID 32102250, 2020). "Moreover, in the previously reported angiographic study, vascular nonperfusion—both anterior and posterior to the tumor—was present in 63% of the VHL patients, and in none without VHL." (PMID 32824842, 2020). "While HIF1α was abundant in nuclei concordantly with defects in VHL, negative staining of its targets carbonic anhydrase IX (CAIX) and glucose transporter GLUT1, usually overexpressed in VHL-associated neoplasms, suggested HIF1α to be present in its inactive (hydroxylated) form." (PMID 30728892, 2019).
tumor (continued). "Our retrospective analyses of human tumor tissue provides the first evidence from a clinical setting that tissue ascorbate levels could moderate HIF activation through stimulation of the HIF hydroxylases, but only in VHL-proficient tumors." (PMID 30555801, 2018). "The ‘hypermethylator’ phenotype of SDHx-mutated tumours is a product of succinate-dependent inhibition of the TET family of DNA demethylases, hence is not observed in VHL-mutated disease." (PMID 29450727, 2018). "Thus after VHL inactivation, HIF induces ISGF3, which is reversed by the loss of secondary tumor suppressors, suggesting that this is a key negative feedback loop in ccRCC." (PMID 30355451, 2018). "Similarly, VHL-mutated PGLs, not those with decreased VHL-gene/mRNA dosage, over-expressed miR-210 and accumulate HIF-1α in most tumor cells." (PMID 28036268, 2017). "Interestingly, 12/48 HRO tumours had no visible alteration of the VHL locus 3p25.3 besides gene losses at other loci in 3p." (PMID 28486536, 2017). "In addition, no markers have been found to correlate to tumor onset age variability and age‐related tumor risks in VHL patients." (PMID 28776935, 2017). "This patient regularly visited the clinic, and no other VHL-related tumor developed." (PMID 27439424, 2016). "VHL could also suppress basal levels of Vascular Endothelial Growth Factor (VEGF) expression, restore hypoxia-inducibility of VEGF expression, and inhibit tumor formation in nude mice." (PMID 27107416, 2016). "For VHL wild-type tumors, other therapy modalities aiming at pVHL non-related pathways controlled by tumor suppressors such as PBRM1, SETD2 or BAP1 may be more appropriate than the common anti-angiogenic treatment." (PMID 27530247, 2016). "In contrast to adenocarcinoma of the lung or colon where mutations in EGFR or K-RAS are the markers clearly predicting the sensitivity of tumor cells to EGFR inhibitors, the presence of VHL mutations is not a clear indication for the use of VEGF/VEGFR inhibitors or other antiangiogenic drugs." (PMID 26500709, 2015). "These alterations could lead to an immune suppressive tumor microenvironment although a correlation of the VHL status with the immune cell infiltration has not yet been determined in detail." (PMID 25890500, 2015). "However, exactly how much of the reduction in tumor growth by GA is due to direct cytotoxicity (VHL-independent) as opposed to the blockade of tumor angiogenesis (VHL-dependent) is not yet known." (PMID 28326255, 2015). "No genetic alterations of the VHL gene were found in our tumor series." (PMID 25490036, 2014). "Our results indicate that there might be other HRGs that mediate the critical oncogenic activity of HIF in RCC, as VEGF or Cyclin D1 overexpression failed to drive efficient tumor growth in VHL+/+ cells as the overexpression of HIF2α did." (PMID 24260413, 2013). "ANGPTL4-786 also failed to change the tumor growth by VHL-/- cells significantly." (PMID 24260413, 2013). "These novel observations may indicate that KAI1 exerts profound metastasis-suppressor activity in the tumor malignancy process via inhibition of CDCP1-mediated Src activation, followed by VHL-induced HIF-1α degradation and, ultimately, decreased VEGF expression." (PMID 22390300, 2012). "Sunitinib elicited a more potent response in 786-O tumours compared with Caki-1, which may be due to the absence of VHL expression in 786-O." (PMID 22015557, 2011). "The remaining 13.4% of cases in which we did not observe evidence of VHL inactivation (VHL wild type cases) may represent a biologically distinct subgroup, one that was observed more frequently in tumor DNA from smokers than never-smokers." (PMID 22022277, 2011). "However, within individual clear cell tumours, subpopulations of cells with and without VHL deletion existed, and VHL-depleted subpopula-tions had different chromosome 3 counts." (PMID 22738081, 2011).